NOB1 (NIN1 (RPN12) binding protein 1 homolog)
Description:
May play a role in mRNA degradation (Probable). Endonuclease required for processing of 20S pre-rRNA precursor and biogenesis of 40S ribosomal subunits (By similarity).
Synonyms: NOB1P; PSMD8BP1; MSTP158; ART-4; MST158
Tractability: Small molecule: a structure with a bound ligand is known. PROTAC: ubiquitination databases record sites on it; its protein half-life has been measured.
Gene: Protein-coding gene on chromosome 16 (69,741,871 to 69,754,942, reverse strand). Ensembl gene ENSG00000141101.
Subcellular location: Nucleus
Subcellular location (Human Protein Atlas): Cytosol; Focal adhesion sites
Pathways (Reactome):
Metabolism of RNA: Major pathway of rRNA processing in the nucleolus and cytosol
Gene Ontology:
Molecular function: protein binding; RNA endonuclease activity
Biological process: maturation of SSU-rRNA; rRNA processing; ribosomal small subunit biogenesis
Cellular component: cytosol; nucleoplasm; preribosome, small subunit precursor; nucleus
Genetic constraint (gnomAD): Loss-of-function variants: 41 observed, 43.13 expected, observed/expected ratio (o/e) 0.95, 90% interval 0.74 to 1.23. The upper end of that interval is the gene's LOEUF score, 1.23, which puts it in group 5 of 6, group 1 being the genes least tolerant of losing a copy. Missense variants: 557 observed, 554.08 expected, observed/expected ratio (o/e) 1.01, 90% interval 0.94 to 1.08. Synonymous variants: 237 observed, 223.19 expected, observed/expected ratio (o/e) 1.06, 90% interval 0.95 to 1.18.
Homologues: Orthologues: chimpanzee NOB1 (99% identical), macaque NOB1 (96% identical), dog NOB1 (91% identical), pig NOB1 (90% identical), rat Nob1 (89% identical), mouse Nob1 (88% identical), guinea pig NOB1 (88% identical), rabbit NOB1 (75% identical), tropical clawed frog nob1 (66% identical), zebrafish nob1 (63% identical), Drosophila melanogaster CG2972 (40% identical), Caenorhabditis elegans nobh-1 (32% identical).
Diseases named in the same sentence as NOB1 in open-access papers:
NOB1 is named in the same sentence as 25 diseases in open-access papers, as found by Europe PMC text mining. Sharing a sentence is not in itself a finding about the gene and the disease. The quoted sentences say what the papers report.
osteosarcoma (9 papers, 2014 to 2023). A usually aggressive malignant bone-forming mesenchymal neoplasm, predominantly affecting adolescents and young adults. "NOB1-knockdown strongly suppressed the growth of osteosarcoma cells and caused G2/M-phase arrest, as confirmed by MTT, colony formation and cell cycle assays." (PMID 24714960, 2014). "Our result also proposed that upregulation of NOB1 predicted poor survival of osteosarcoma patients." (PMID 32357945, 2020). "Long non-coding RNA small nucleolar RNA host gene 1 has been previously reported to regulate the NOB1 expression by binding to miR-326 in osteosarcoma." (PMID 32670874, 2020). "It has been reported that downregulation of NOB1 inhibits cell proliferation in prostate cancer, oral squamous cell carcinoma, and osteosarcoma." (PMID 31068824, 2019). "In addition, low expression of miR-363 or overexpression of NOB1 predicted poor prognosis of osteosarcoma patients." (PMID 32357945, 2020). "Chi-square test was performed to calculate the P value, and it was illuminated that the expression of miR-363 had a negative association with tumor size (P < 0.05), TNM stage (P < 0.05), lymph node metastasis (P < 0.05), and the expression of NOB1 in osteosarcoma tissues (P < 0.05)." (PMID 32357945, 2020). "Besides, it is reported that SNHG1 increased the expression of human oncogene nin-one binding protein (nob1) by sponging miR-326 as ceRNA, and ultimately promoted the growth, migration, and invasion of osteosarcoma cells." (PMID 31383786, 2019). "All the results demonstrated that low expression of NOB1 inhibited the migration, invasion, and EMT of osteosarcoma cells, which were consistent with the results when miR-363 was overexpressed." (PMID 32357945, 2020). "In osteosarcoma, small nucleolar RNA host gene 1 (SNHG1) regulates the level of NIN1 binding protein 1 homolog (NOB1) by sponging miR-326 and promotes the tumorigenesis of osteosarcoma cell." (PMID 32425696, 2020).
glioma (6 papers, 2013 to 2022). A benign or malignant brain and spinal cord tumor that arises from glial cells (astrocytes, oligodendrocytes, ependymal cells). "Similar to NOB1 silencing by shRNA, overexpression of miR-326 in human glioma cell lines (A172 and U373) caused cell cycle arrest at the G1 phase, delayed cell proliferation and enhanced apoptosis." (PMID 23869222, 2013). "Moreover, the expression of NOB1 might be associated with tumor grades as well as the prognosis of glioma patients." (PMID 23869222, 2013). "Moreover, NOB1 expression might be associated with tumor grade as well as the prognosis of glioma patients." (PMID 23869222, 2013). "Previous study showed that miR-326 acted as a tumor-suppressive factor by down-regulating pyruvate kinase type M2 (PKM2) and Nin one binding protein (NOB1) in human glioma." (PMID 26183397, 2015). "In the present study, the human Nin one binding protein (NOB1) was identified as a direct target of miR-326 and a potential oncogene in human glioma." (PMID 23869222, 2013). "The expression of NOB1 mRNA in high-grade gliomas was approximately 4-fold (P = 0.017) higher, and that of low-grade gliomas was 1.5-fold (P = 0.032) higher than that of normal brain tissues." (PMID 23869222, 2013). "The present results showed that NOB1 is highly expressed in glioma cell lines and tissues, whereas its expression is decreased in normal brain tissue." (PMID 23869222, 2013). "Moreover, miR-326 may inhibit cell colony formation and reduce growth of a xenograft tumor, thus indicating that miR-326 and NOB1 are important for glioma progression both in vitro and in vivo." (PMID 30583549, 2018). "Taken together, these results establish miR-326 as a regulator of NOB1 expression and MAPK pathway activity in human glioma, with potential therapeutic implications." (PMID 23869222, 2013). "Furthermore, its expression has been shown to inhibit tumorigenesis through direct targeting of Nin one binding protein (NOB1) and the MAPK pathway in glioma cells." (PMID 34513655, 2021).
cervical cancer (5 papers, 2020 to 2022). A primary or metastatic malignant neoplasm involving the cervix. "NOB1 acted as an oncogene and was upregulated in a variety of cancers that include cervical cancer, gastric cancer, epithelial ovarian cancer, and non-small cell lung cancer." (PMID 32357945, 2020). "NOB1 was upregulated and acted as an oncogene in a variety of cancers including cervical cancer, gastric cancer, epithelial ovarian cancer, and non-small cell lung cancer." (PMID 32357945, 2020). "NOB1 may be an oncogene, which promotes the proliferation of cervical cancer, papillary thyroid cancer and other malignant tumors." (PMID 35150481, 2022).
breast carcinoma (3 papers, 2022 to 2024). "In cluster 1, breast cancer cell markers, including Nob1, Vmp1, Crk, Ckap2, Parp14 and Mfn1, were detected among the top cluster markers." (PMID 39054536, 2024). "Heat shock protein 1B, NOB1 and CRIP1 were upregulated while BCLAF1 was downregulated in breast cancer after sublethal heat treatment." (PMID 35150481, 2022).
lung carcinoma (3 papers, 2019 to 2020). "Proto-oncogenes NOB1 and phox2a were also targeted by miR-326 in gastric cancer and lung cancer." (PMID 32766125, 2020). "For instance, in lung cancer, miR-646 suppresses cell proliferation and metastasis by negatively regulating the EGFR/Akt pathway; in colorectal cancer, miR-646 represses NOB1 to inhibit cancer progression." (PMID 32669977, 2020).
prostate carcinoma (3 papers, 2019 to 2020). A carcinoma that arises from epithelial cells of the prostate gland. "In addition, NOB1 gene silencing can inhibit tumor growth by inducing apoptosis in human colorectal cancer and prostate cancer." (PMID 32357945, 2020). "In addition, knockdown of NOB1 suppressed the malignant transformation of prostate cancer." (PMID 32357945, 2020). "MiR-195-5p has been identified to interact with NOB1, NOTCH2 and CCNE1 in several cancers, while miR-195-5p has not been investigated in prostate cancer." (PMID 32440687, 2020).
Obesity (1 paper, 2015). Accumulation of substantial excess body fat. "Moreover, when combined with the obesity QTL, Nob1, the diabetogenic effect from Nidd/SJL was greatly enhanced by a high-fat diet (HFD), which strongly suggests that Nidd/SJL contains a gene for obesity-associated diabetes." (PMID 26232096, 2015).
tumor (13 papers, 2013 to 2022). "Among these targeted miRNAs, miR-646 was a potential candidate that interacts with NOB1, which has shown potential efficacy in regulating tumor cell biology, especially invasion and metastasis." (PMID 31950059, 2019). "miR-326 is a recognized tumor-suppressing miRNA, in fact among its targets there are Gli2, Smo, Notch1, Notch2 and Nob1." (PMID 28716052, 2017). "miR139-3p may act as a tumor suppressor that inhibits cell migration, proliferation, and invasion, and induces cell apoptosis through the downregulation of NOB1 expression." (PMID 35954205, 2022).
cancer (10 papers, 2016 to 2023). A tumor composed of atypical neoplastic, often pleomorphic cells that invade other tissues. "In addition, Nob1 is a potential biomarker in cancer, and the expression of Nob1 in cancer tissues is significantly increased and affects the prognosis of cancer." (PMID 37924155, 2023). "NOB1 has been reported to be an important regulator in several cancers." (PMID 31068824, 2019). "We assessed whether downregulation of hCINAP blocks tumorigenesis because of the essential role of hCINAP in Nob1-mediated 18S rRNA processing and the inhibitory effect of hCINAP depletion on ribosome assembly in human cancer cells." (PMID 27477389, 2016).
NOB1 also shares sentences with these, for which no sentence is quoted: colorectal cancer (2 papers); epithelial ovarian cancer (2); gastric cancer (2); ovarian cancer (2); atopic dermatitis (1); clear cell renal carcinoma (1); glioblastoma (1); gynecological cancers (1); infection (1); laryngeal carcinoma (1); leukemia (1); non-small cell lung carcinoma (1); oral squamous cell carcinoma (1); papillary thyroid cancer (1); renal carcinoma (1); rheumatoid arthritis (1).